MEF2C-AS1 (MEF2C antisense RNA 1)
Gene: Long non-coding RNA gene on chromosome 5 (88,883,276 to 89,467,616, forward strand). Ensembl gene ENSG00000248309.
Diseases named in the same sentence as MEF2C-AS1 in open-access papers:
MEF2C-AS1 is named in the same sentence as 2 diseases in open-access papers, as found by Europe PMC text mining. Sharing a sentence is not in itself a finding about the gene and the disease. The quoted sentences say what the papers report.
tumor (1 paper, 2022). "A novel lncRNA gene MEF2C antisense RNA 1 (MEF2C-AS1), located at 5q14.3, has been identified to be downregulated and to play tumor suppressor roles in diffuse gastric cancer (DGC), cervical cancer (CC), and BC by inhibiting cell proliferation and aggressive tumor phenotypes." (PMID 36064442, 2022).
MEF2C-AS1 also shares sentences with these, for which no sentence is quoted: cervical cancer (1 paper).